IGFBP6 (insulin like growth factor binding protein 6)
Diseases named in the same sentence as IGFBP6 in open-access papers (continued):
Sharing a sentence is not in itself a finding about the gene and the disease.
Sepsis (continued). "(b) TLR2/4-mediated IGFBP6 regulation represents an unexplored mechanistic axis for sepsis progression worthy of further exploration." (PMID 40892465, 2025). "In this study, reduced SF IGFBP6 was identified within the sepsis group compared to other joint pathologies." (PMID 31028944, 2019). "Lactotransferrin (LTF) abundance was increased in sepsis compared to all other groups and insulin-like growth factor-binding protein 6 (IGFBP6) abundance decreased in sepsis compared to other disease groups." (PMID 31028944, 2019). "Elevated synovial abundance of LTF and decreased IGFBP6 were both found to distinguish synovial sepsis from all other study groups." (PMID 31028944, 2019). "Despite these immunoregulatory connections, the functional implications of IGFBP6 in sepsis pathophysiology remained unexplored, to our knowledge, until our study uncovered its critical role in driving septic progression through distinct immune modulation mechanisms." (PMID 40892465, 2025). "(d) Future studies employing tissue-specific or temporal IGFBP6 modulation could further dissect how resistance and tolerance mechanisms are differentially regulated during sepsis progression." (PMID 40892465, 2025). "Depletion of endogenous IGFBP6 improves outcomes in murine polymicrobial sepsis." (PMID 40892465, 2025). "(b) IGFBP6 exacerbates sepsis by impairing macrophage chemotaxis and antimicrobial functions." (PMID 40892465, 2025). "IGFBP6 facilitates the pathogenesis and progression of sepsis." (PMID 40892465, 2025). "Collectively, these data establish that IGFBP6 compromises host antimicrobial defense by impairing macrophage recruitment to infection foci, thereby exacerbating systemic pathogen dissemination during sepsis." (PMID 40892465, 2025). "IGFBP6 impairs the chemotaxis of macrophages in sepsis pathogenesis." (PMID 40892465, 2025). "Intervention strategies targeting IGFBP6-mediated signaling may offer transformative approaches for sepsis management." (PMID 40892465, 2025). "(c) PHB2/STAT1/CCL2 axis modulation reverses IGFBP6-mediated sepsis pathology." (PMID 40892465, 2025). "To investigate the role of IGFBP6 in sepsis pathogenesis, we established a murine sepsis model induced by cecal ligation and puncture (CLP) and observed significant elevation of IGFBP6 levels in the serum, peritoneal lavage fluid (PLF), and key organs (lung and spleen) during sepsis progression." (PMID 40892465, 2025). "In adult cohorts, serum IGFBP6 levels at admission were significantly elevated in patients with sepsis versus patients with non-sepsis infections and healthy volunteers across the discovery and validation cohorts." (PMID 40892465, 2025). "Stratified analysis revealed significantly higher concentrations of IGFBP6 in septic shock than in sepsis and in nonsurvivors than in survivors." (PMID 40892465, 2025). "The AUC of IGFBP6 for differential diagnosis of sepsis and non-septic infection was 0.67 (95% CI, 0.57 to 0.78) and 0.78 (95% CI, 0.73 to 0.84), respectively." (PMID 40892465, 2025). "Postoperative sepsis significantly alters the growth hormone/IGF axis, reducing GH-dependent molecule secretion (i.e. IGFBP3) and increasing GH-independent molecule secretion (i.e. IGFBP6)." (PMID 31028944, 2019). "Notably, TLR signaling pathway analysis revealed that TLR2 and/or TLR4 deficiency substantially attenuated IGFBP6 expression in PLF, pulmonary tissue, macrophages, and epithelial cells during sepsis, establishing TLR2/4-mediated regulation of IGFBP6 production." (PMID 40892465, 2025).
triple-negative breast carcinoma (2 papers, 2019 to 2025). An invasive breast carcinoma which is negative for expression of estrogen receptor (ER), progesterone receptor (PR), and human epidermal growth factor receptor 2 (HER2). "Knockdown of IGFBP-6 in a triple-negative breast cancer cell line, MDA-MB-231, also resulted in a decrease in Cyclin B1 accumulation, demonstrating that our observations are not cell line specific." (PMID 41419198, 2025).
acute lung injury (1 paper, 2025). A condition of lung damage that is characterized by bilateral pulmonary infiltrates (pulmonary edema) rich in neutrophils, and in the absence of clinical heart failure. "Among the marker genes of branch II, Igfbp6 shows transcriptional changes in acute lung injury (ALI)." (PMID 41041455, 2025).
adenomyosis (1 paper, 2022). The growth of endometrial tissue inside the muscular wall of the uterine corpus. "We also did qPCR on the adenomyosis pain group and the non-pain group and discovered that several mRNAs associated with nerve growth and neuroinflammatory factors, NEFM, GATA2, HMGA1, and IGFBP6, were considerably more strongly expressed in the adenomyosis pain group than in the non-pain group." (PMID 36532077, 2022).
AIDS (1 paper, 2015). A syndrome resulting from the acquired deficiency of cellular immunity caused by the human immunodeficiency virus (HIV). "After normalization by the β-actin, the expression level of IGFBP6 was down-regulated by 65.9% in HIV/AIDS patients relative to normal controls (P = 0.04, one sided Mann-Whitney U test) while SATB2 was down-regulated by 57.1% (P = 0.027)." (PMID 26039376, 2015). "Consistent with our previous results, we found that the relative expression levels of both IGFBP6 and SATB2 were low in all groups of HIV/AIDS patients compared with normal groups." (PMID 26039376, 2015). "We found that IGFBP6 and SATB2 were significantly down-regulated in HIV-infected CEM*174 cells and 3 different cohorts of HIV/AIDS patients while their promoters were predominantly hyper-methylated compared with normal controls." (PMID 26039376, 2015).
Arthritis (1 paper, 2020). Inflammation of a joint. "IGFBP4 (144 ng), with IGFBP6 (85 ng) and 3 (10 ng), was shown to balance the IGF-dependent induction of CD4+FOXP3+ Tregs given by MSC-conditioned medium in arthritis." (PMID 32345351, 2020).
asthma (1 paper, 2023). "IGFBP-6 is involved in the pathophysiology of asthma, as demonstrated in different genome-wide association studies, the candidate genes approach, and the genomic expression and linkage analysis which identified over 300 genes associable with asthma pathophysiology, including IGFBP-6." (PMID 36902237, 2023). "To summarize, IGFBP-6 levels are significantly higher in asthma after ICS therapy." (PMID 36902237, 2023).
autoimmune disease (1 paper, 2018). A disorder resulting from loss of function or tissue destruction of an organ or multiple organs, arising from humoral or cellular immune responses of the individual to their own tissue constituents. "Finally, we discuss the role of IGFBP‐6 in autoimmune disease and how novel mechanistic insights could lead to exploit thermal stress‐related mechanisms in the context of cancer therapy." (PMID 30117676, 2018).
Autoimmunity (1 paper, 2017). The occurrence of an immune reaction against the organism's own cells or tissues. "Given that IGFBP-6 has recently been associated with several pathological conditions, further studies are warranted in order to evaluate how IGFBP-6 is governing chemotaxis and whether this protein might also play a pathogenetic role in autoimmunity." (PMID 28977828, 2017).
bone metastasis (1 paper, 2022). Transfer of a neoplasm from its primary site to bones. "In the validation dataset of GSE14020, GJA1, IGFBP6, ITGBL1, SLC44A1, and TGFBI expressions in the bone-metastasis group were different from those in the control group." (PMID 36046013, 2022).
brain tumors (1 paper, 2023). "Furthermore, in order to evaluate the potential diagnostic ability of IGFBP6 gene expression to discriminate against the brain tumors stages, we performed a Receiver operating characteristic (ROC) analysis." (PMID 35654889, 2023). "According to these results, we investigated the prognostic potential of IGFBP6 expression in the progression of main brain tumors." (PMID 35654889, 2023).
cardiac hypertrophy (1 paper, 2025). "Conditional knockout of IGFBP6 in cardiac fibroblasts and myofibroblasts markedly attenuated post-MI fibrotic remodeling, ventricular dysfunction, and ISO-induced cardiac hypertrophy and fibrosis." (PMID 41208894, 2025).
cholangiocarcinoma (1 paper, 2026). A carcinoma that arises from the intrahepatic biliary tree (intrahepatic cholangiocarcinoma) or from the junction, or adjacent to the junction, of the right and left hepatic ducts (hilar cholangiocarcinoma). "Cholangiocarcinoma (CCA) microenvironment reviews compiling single-cell and bulk data likewise list IGFBP-6 among fibroblast-enriched transcripts in CAF subsets linked to inflammation and matrix remodeling." (PMID 41511360, 2026). "In cholangiocarcinoma specifically, focused reviews emphasize CAF dominance and growth-factor handling as druggable stromal functions, situating IGF/IGFBP biology—including IGFBP-6—within tractable paracrine networks that might be leveraged for therapy or biomarker development." (PMID 41511360, 2026).
chronic hepatitis (1 paper, 2026). An active inflammatory process affecting the liver for more than six months. "Biomarker-wise, the observed decrease in serum IGFBP-6 in HCC relative to chronic hepatitis encourages evaluation of IGFBP-6 as an adjunct classifier, but studies must control for underlying etiology, fibrosis stage, and antiviral treatment to avoid confounding axis-level shifts." (PMID 41511360, 2026). "In one antibody-array study, circulating IGFBP-6 showed only a modest decrease in patients with HCC (mean ~15%) than in those with chronic hepatitis, and this signal was not validated by an orthogonal quantitative assay." (PMID 41511360, 2026).
depression (1 paper, 2023). "Finally, we have found no study addressing peripheral IGFBP-4, IGFBP-5 and IGFBP-6 levels in the context of human depression." (PMID 37894932, 2023).
desmoid tumor (1 paper, 2026). A desmoid tumor (DT) is a benign, locally invasive soft tissue tumor associated with a high recurrence rate but with no metastatic potential. "In desmoid tumors (aggressive fibromatosis), stabilized β-catenin represses IGFBP-6 expression, and promoter/EMSA studies identified functional β-catenin/T-cell factor (TCF)-responsive elements in the human IGFBP-6 promoter, supporting direct transcriptional repression by the β-catenin/TCF complex." (PMID 41511360, 2026).
diabetic nephropathy (1 paper, 2024). "Subsequent investigations added a role of IGFBP6 and IGFBP3 in other kidney diseases such as diabetic nephropathy, glomerulosclerosis, and IgA nephropathy." (PMID 39081308, 2024).
endometrial cancer (1 paper, 2023). Primary or metastatic malignant neoplasm involving the endometrium (mucous membrane that lines the endometrial cavity). "We found that only the mutation of IGFBP3 will affect its expression in endometrial cancer, and the mutation of IGFBP6 will affect its expression in skin melanoma." (PMID 37088808, 2023).
endometrioid ovarian cancer (1 paper, 2020). "In addition, the IGFBP4 protein expression was upregulated in SOC, and the IGFBP6 protein expression was upregulated in both of SOC and endometrioid ovarian cancer (EOC) tissues." (PMID 33282953, 2020).
esophageal cancer (1 paper, 2020). A primary or metastatic malignant neoplasm involving the esophagus. "Loss of IGFBP1-5 expression was frequently found in esophageal cancer cells, while IGFBP6 was expressed in all cell lines (data not show)." (PMID 32041673, 2020). "Increased expression of IGF1R, IGFBP3, IGFBP4, IGFBP7, and IGFBP8 was reported in human esophageal cancer, while the expression of IGFBP2 and IGFBP6 was reduced." (PMID 32041673, 2020).
fibrosis (1 paper, 2022). the formation of excess fibrous connective tissue in an organ or tissue in a reparative or reactive process. "Dermal fibroblasts treated with a combination of TGF-β1 and the monocyte chemoattractant protein 3 (MCP-3), a protein that is up-regulated in fibrosis, led to a high and significant IGFBP-6 upregulation." (PMID 35457175, 2022).
Hepatitis (1 paper, 2008). Inflammation of the liver. "We identified 7 proteins that significantly differentiate HCC patients from hepatitis patients (p < 0.05) (AFP, CTNNB, CSF1, SELL, IGFBP6, IL6R, and VCAM1)." (PMID 19578489, 2008).
herpesvirus infections (1 paper, 2022). "Both vascular endothelial growth factor-C (VEGF-C) and insulin-like growth factor binding protein-6 (IGFBP-6) have been shown to be upregulated during herpesvirus infections." (PMID 35911725, 2022).
Hyperglycemia (1 paper, 2021). An increased concentration of glucose in the blood. "In our analysis, the association with DPN remained unchanged for sTNFRI, sTNFRII, sIL2Rα, IGFBP6 and CRP, after adjusting for HbA1c levels in study subjects, suggesting that factors other than hyperglycemia are also involved in pathogenesis of DPN." (PMID 33868296, 2021).
hypothyroidism (1 paper, 2025). Abnormally low levels of thyroid hormone. "Interestingly, however, while IGFBP3 was impacted by fetal hypothyroidism, there was minimal to no impact on expression of the highly related genes IGFBP5 and IGFBP6." (PMID 40693299, 2025).
infarction (1 paper, 2025). A localised pathological necrosis of tissue resulting from obstruction of the blood supply usually by a thrombus, an embolus, or vascular torsion. "Histological staining showed that IGFBP6 knockout in the myofibroblasts decreased the infarction size post-MI and suppressed adverse remodeling in the left ventricle." (PMID 41208894, 2025). "Our immunofluorescence and subcellular fractionation data revealed that IGFBP6 translocated to the nucleus via NLS signaling upon TGF-β1 stimulation in the MI infarction areas." (PMID 41208894, 2025).
ischemic cardiomyopathies (1 paper, 2025). "Our findings establish cardiac fibroblast-derived IGFBP6 as a novel amplifier of fibrotic signaling cascades and propose a targetable axis for therapeutic intervention in ischemic cardiomyopathy." (PMID 41208894, 2025). "To investigate the role of IGFBP6 in cardiac fibrosis, we reanalyzed the RNA-seq dataset from patients with ischemic cardiomyopathies (ICM: GSE145154)." (PMID 41208894, 2025). "RNA-seq data from ischemic cardiomyopathy patients (GSE145154) further revealed enriched IGFBP6 expression specifically in CFs, but not in endothelial cells and other cell types." (PMID 41208894, 2025).
kidney failure (1 paper, 2025). An acute or chronic condition that is characterized by the inability of the kidneys to adequately filter the blood. "While there is no previous evidence that IGFBP6 is deleterious to kidney function, its gene expression is upregulated in CKD and its levels have been shown to decrease in adults with kidney failure requiring kidney replacement therapy post-transplantation." (PMID 40342947, 2025).
lupus (1 paper, 2018). "In SLE, IGFBP2, IGFBP4 and IGFBP6 were discovered by array-based proteomic screening as diagnostic biomarkers for lupus." (PMID 30214426, 2018).
medulloblastoma (1 paper, 2013). A malignant, invasive embryonal neoplasm arising from the cerebellum. "Protein levels of IGFBP-4 and IGFBP-6 were also noted to be significantly elevated in the CSF of medulloblastoma patients (p = 0.011 and p = 0.010, respectively)." (PMID 24400253, 2013).
mood disorder (1 paper, 2011). A cognitive disorder a disturbance in which the person's mood is hypothesized to be the main underlying feature. "Another couple of interesting genes was Igfbp6 and Igfbp2 which have been shown to be involved in mood disorders and therefore could also have relevance to drug addiction given the interrelationship between both psychopathological spectra." (PMID 21886580, 2011).
muscular dystrophies (1 paper, 2017). "Further investigation of the balance between IGFs and IGFBP-6 in PMSC myogenesis and delineating the receptors and signaling mechanisms governing muscle lineage development and regeneration will improve the success of cellular therapies in muscular dystrophies." (PMID 29387091, 2017).
myocardial infarction (1 paper, 2025). Gross necrosis of the myocardium, as a result of interruption of the blood supply to the area, as in coronary thrombosis. "In the present study, we identified significant upregulation of IGFBP6 in three distinct cardiac fibrosis models (myocardial infarction, isoproterenol-induced injury, and transverse aortic constriction)." (PMID 41208894, 2025). "Serum IGFBP6 levels in patients with chronic myocardial infarction (MI) were quantified via ELISA." (PMID 41208894, 2025).
myopia (1 paper, 2023). "Further analysis using an insulin microarray resulted that the levels of insulin and those related factors including IGF2, IGF-2R, IGF binding protein 1 (IGFBP-1), IGFBP-2, IGFBP-3, IGFBP-4 and IGFBP-6 were markedly increased in patients with pathogenic myopia as compared with the controls." (PMID 38203671, 2023).
pancreatic adenocarcinoma (1 paper, 2010). "Numerous genes were overexpressed, some of which have previously been implicated in pancreatic adenocarcinoma (GATA6, IGFBP3, IGFBP6), while others were detected for the first time (MEMO1, RIOK3)." (PMID 20553613, 2010).
periodontitis (1 paper, 2026). An acute or chronic inflammatory process that affects the tissues that surround and support the teeth. "IGFBP-6 levels were reduced intracellularly but elevated in plasma in periodontitis, and similar patterns were observed in lipopolysaccharide-treated cells." (PMID 42120549, 2026).
portal hypertension (1 paper, 2026). Increased blood pressure in the portal venous system. "We then evaluate experimental and clinical data linking IGFBP-6 to steatotic liver disease, inflammation, and fibrogenesis, including putative roles in hepatocyte stress responses, stellate cell activation, and extracellular matrix remodeling." (PMID 41511360, 2026). "Biochemical overviews underscore that IGFBP-6 is uniquely IGF-II-preferring among IGFBPs, so any post-translational modification that weakens IGF-II affinity would be expected to have disproportionate consequences for IGF signaling in liver disease." (PMID 41511360, 2026).
preeclampsia (1 paper, 2025). Preeclampsia is a hypertensive disorder of pregnancy that is characterized by new-onset hypertension with proteinuria presenting after 20 weeks of gestation, and depending on mild or severe forms may initially present with severe headache, visual disturbances, and hyperreflexia. "For example, we found that IGFBP6 was upregulated in early onset preeclampsia and downregulated in accreta decidual cells." (PMID 41141914, 2025).
psoriasis (1 paper, 2026). An autoimmune condition characterized by red, well-delineated plaques with silvery scales that are usually on the extensor surfaces and scalp. "The levels of fasting glucose, insulin, IGFBP3, and IGFBP6 were higher in patients with psoriasis, while the levels of IGF-1, IGF-1R, and IGBP4 were higher in controls." (PMID 41635444, 2026).
pulmonary fibrosis (1 paper, 2022). Chronic progressive interstitial lung disorder characterized by the replacement of the lung tissue by connective tissue, leading to progressive dyspnea, respiratory failure, or right heart failure. "In the murine model of bleomycin-induced pulmonary fibrosis, we observed upregulation of Igf1, transient upregulation of Igfbp4 and downregulation of Igfbp6." (PMID 35741102, 2022).
pyrexia (1 paper, 2020). "We also have not studied whether circulating EVs transport IGFBP-6 in vivo in patients with pyrexia, and this clinical study will have to be performed." (PMID 32580339, 2020).
schizophrenia (1 paper, 2022). A major psychotic disorder characterized by abnormalities in the perception or expression of reality. "Further metabolic dysregulation was detected as an upregulation in IGFBP6 in schizophrenia and a decrease in IGF2 and IGFBP3/5/7/ALS." (PMID 34741130, 2022).